ITGA5 (integrin subunit alpha 5)
Diseases named in the same sentence as ITGA5 in open-access papers (continued):
Sharing a sentence is not in itself a finding about the gene and the disease.
cervical cancer (9 papers, 2020 to 2025). A primary or metastatic malignant neoplasm involving the cervix. "High ITGA5 level was significantly correlated with increased risk in terms of overall survival and advanced disease stage in cervical cancer patients." (PMID 36999964, 2023). "ITGA5‐associated differentially expressed genes linked ITGA5 to angiogenesis, and immunohistochemistry showed a positive correlation between ITGA5 and microvascular density in cervical cancer tissues." (PMID 36999964, 2023). "In present study, immunohistochemistry suggested that ITGA5 is closely associated with the OS and progression of cervical cancer patients." (PMID 36999964, 2023). "By using bioinformatics methods, we comprehensively explored the correlations of 19 integrin superfamily members with the overall survival (OS) of cervical cancer patients and found that integrin alpha 5 (ITGA5) was the highest risk factor for prognosis." (PMID 36999964, 2023). "In conclusion, our study reveals that ITGA5 promotes angiogenesis in cervical cancer and is associated with a poor prognosis in patients." (PMID 36999964, 2023). "In the multivariate Cox regression, N1 stage, high-risk score, and the genes TNF, ITGA5, CXCL1, and CCL20 were observed to be significantly associated with increased risk in cervical cancer patients." (PMID 40517358, 2025). "In cervical cancer, ITGA5 influences tumor cell responses to CXCL12 by regulating CXCR4 expression, thereby promoting cell migration and invasion." (PMID 40517358, 2025). "It identifies CST7, along with IL1B and ITGA5, as three crucial genes that play a vital role in the evolution of cervical cancer." (PMID 39552709, 2024). "The results of pairwise gene correlation analysis of GEPIA2 data showed that the expression of FN1 was positively related to ITGA5 expression in cervical cancer." (PMID 36999964, 2023). "We found that decreased ITGA5 expression inhibited the activation of p‐AKT in cervical cancer cells." (PMID 36999964, 2023). "By up-regulating CST7 and down-regulating IL1B and ITGA5, cervical cancer cells’ proliferation ability and invasion ability were successfully reduced." (PMID 36969161, 2023). "To explore the potential role of IL1b, CST7, and ITGA5 in the immune microenvironment, we downloaded single-cell data of cervical cancer in GEO to validate our results and explore a more precise transcriptional landscape." (PMID 36969161, 2023). "Given that HPV has been associated with angiogenesis in cervical cancer, we analyzed the ITGA5 expression in HPV‐positive versus HPV‐negative cervical cancers using GSE171894 single‐cell RNA‐seq dataset." (PMID 36999964, 2023). "Our findings suggested that the angiogenic function of ITGA5 in cervical cancer was through increasing VEGFA expression." (PMID 36999964, 2023). "We then performed cellular experiments to investigate the role of CST7, IL1B and ITGA5 in cervical cancer cells." (PMID 36969161, 2023). "ITGA5 promotes angiogenesis in cervical cancer by AKT/VEGFA axis and Fibronectin playscritical role in this pathway." (PMID 36999964, 2023). "Both GEPIA2 and Kaplan–Meier plotter analyses showed a significantly poorer OS in cervical cancer patients with high ITGA5 expression." (PMID 36999964, 2023). "To further explore the effects of ITGA5 in cervical cancer, we analyzed the correlation between ITGA5 IHC score and clinicopathological characteristics of patients." (PMID 36999964, 2023). "ITGA5 promotes angiogenesis and possibly be a potential predictive biomarker for poor survival of patients in cervical cancer." (PMID 36999964, 2023). "Integrin α5 (Itga5) was also reported to promote angiogenesis through VEGFA in cervical cancer." (PMID 39000126, 2024). "Moreover, future in vivo investigation of ITGA5‐mediated angiogenesis in cervical cancer is necessary and investigations are still required to identify the underlying mechanism." (PMID 36999964, 2023). "Integrin alpha 5 (ITGA5) is correlated with the prognosis of cervical cancer patients." (PMID 36999964, 2023).
cervical cancer (continued). "We propose that ITGA5 could serve as a novel promising molecular therapeutic target for treating patients with advanced cervical cancer." (PMID 36999964, 2023). "Furthermore, experimental models in vitro suggest that ITGA5 promotes angiogenesis in cervical cancer via the AKT/VEGFA pathway." (PMID 36999964, 2023). "In addition, experiments in vitro were conducted to investigate the functional role of ITGA5 in cervical cancer." (PMID 36999964, 2023). "The results revealed that ITGA5 knockdown in cervical cancer cells could significantly inhibit HUVECs to form tubes and sprouts." (PMID 36999964, 2023). "ITGA5 protein expression was detected in 155 human cervical cancer tissues by immunohistochemistry." (PMID 36999964, 2023). "In our study, RNA‐seq data were acquired from the TCGA database to identify differentially expressed genes (DEGs) between cervical cancer patients with high and low ITGA5 expression levels, and a total of 217 significant DEGs, including 149 upregulated and 68 downregulated DEGs, were isolated." (PMID 36999964, 2023). "Overall, these results indicate a critical role of ITGA5 in cervical cancer angiogenesis." (PMID 36999964, 2023). "Furthermore, based on TCGA cohort, univariate and multivariate Cox regression analyses showed that ITGA5 level, tumor size, and lymph node metastasis were independent predictive factors for OS of cervical cancer patients." (PMID 36999964, 2023). "Here, we identify ITGA5 as the most survival‐related integrin superfamily member in cervical cancer and unravel its role in sprouting angiogenesis and VEGFA expression regulation, suggesting that ITGA5 is a potential mediator of angiogenesis in cervical cancer." (PMID 36999964, 2023). "Moreover, we performed IHC staining of ITGA5 in 155 cervical cancer tissues." (PMID 36999964, 2023). "However, the role of ITGA5 in cervical cancer has been rarely reported thus far." (PMID 36999964, 2023). "To confirm the correlation between ITGA5 and angiogenesis, we performed IHC for CD31 to identify microvessels in 57 human cervical cancers." (PMID 36999964, 2023). "Since fibronectin (FN1) is the main ligand for ITGA5, we investigated the influence of the presence of FN1 on ITGA5‐mediated angiogenesis in cervical cancer." (PMID 36999964, 2023). "After validation by quantitative RT-PCR, we discovered that diminished miR-128 in WT-HeLa or WT-CaSki cells markedly increased the expression levels of ITGA5, ITGB5, sLex, CEACAM-6, MMP9, and MMP23 in WT-HeLa and WT-CaSki cervical cancer cell clones." (PMID 33379338, 2020). "We further validated that the overexpression of miR-128 markedly decreased ITGA5, ITGB5, sLex, CEACAM-6, MMP-9, and MMP-23 in SSR-HeLa and SSR-CaSki cervical cancer cell clones." (PMID 33379338, 2020). "According to Transwell data, the capacity of cervical cancer cells to migrate was dramatically reduced when IL1B and ITGA5 were knocked down and CST7 was overexpressed in comparison to the control group, similarly, the invasive ability of cervical cancer cells was significantly down-regulated." (PMID 36969161, 2023). "We also analyzed the correlation of ITGA5 with anti‐angiogenesis genes THBS2, PTEN, SERPZNF1, and IL‐10 in cervical cancer based on TCGA dataset, but the correlations were rather modest as the R values ranged between −0.011 and 0.16, though the p values were less than 0.05." (PMID 36999964, 2023). "To verify whether FN1 could promote ITGA5‐mediated angiogenesis in vitro, we downregulated FN1 in cervical cancer cells transfected with siRNAs (siFN1 vs. siNC) or cultured cells in FN1‐containing substrate (+fibronectin vs. control) to manipulate the FN1‐ITGA5 interaction." (PMID 36999964, 2023).
cervical cancer (continued). "According to the expression heatmaps of integrins in GSE168009 dataset, which includes four cervical cancer patients with no durable benefit from concurrent chemoradiotherapy and five patients with durable clinical benefit, ITGA5 expression was significantly higher in the no benefit group." (PMID 36999964, 2023). "However, whether ITGA5 plays an active role in cervical cancer progression or not remains unknown." (PMID 36999964, 2023).
head and neck squamous cell carcinoma (9 papers, 2021 to 2026). A squamous cell carcinoma that arises from any of the following anatomic sites: lip and oral cavity, nasal cavity, paranasal sinuses, pharynx, larynx, and salivary glands. "One of the markers of invasiveness in head and neck squamous cell carcinoma has been identified as ITGA5." (PMID 37822877, 2023). "ITGA5 is upregulated in head and neck squamous cell carcinoma (HNSCC)." (PMID 42255482, 2026). "Another study by Li defined seven‐gene NET‐related signature, including ITGA5, NIFK, NUTF2, PDGFα, TNFRSF12, LINC00460 and LINC02454, for head and neck squamous cell carcinoma through the TCGA and ICGC cohorts (p‐value < 0.05)." (PMID 39730971, 2024). "We previously showed that p-EMT genes such as SERPINE1, ITGA5, TGFBI, P4HA2, CDH13, and LAMC2 are potent poor prognostic markers in head and neck squamous cell carcinoma (HNSCC) patients by bioinformatic analysis." (PMID 34294795, 2021). "The aim of this study was to detect the expression levels of α-Actinin 1 (ACTN1) and ITGA5 in HNSCC and to explore how ACTN1/ITGA5 regulated the proliferative and invasive abilities, as well as the EMT of Head and neck squamous cell carcinoma (HNSCC) cells." (PMID 36742137, 2023).
triple-negative breast carcinoma (8 papers, 2019 to 2025). An invasive breast carcinoma which is negative for expression of estrogen receptor (ER), progesterone receptor (PR), and human epidermal growth factor receptor 2 (HER2). "The HIF-1α/miR-142-3p/LOX/ITGA5 pathway has been studied in the context of chemotherapy resistance, particularly in triple-negative breast cancers." (PMID 39857068, 2025). "In particular, the highest ITGA5 mRNA levels were observed in claudin-low, triple-negative breast cancer cell lines (p < 0.01)." (PMID 33420367, 2021). "In this respect, ITGA5 silencing in Hs578T cells (a triple-negative breast cancer cell line expressing high ITGA5 levels) recapitulates inhibitory effects of miR-30s on bone metastasis formation in vivo." (PMID 33420367, 2021). "Moreover, reduced expression of ITGA5, induced by re-expression of miR-205, reportedly inhibits cancer stem cell-like properties in triple-negative breast cancer." (PMID 36765401, 2023). "Moreover, based on the high expression of ITGA5 in triple-negative breast cancer (TNBC) and its lung metastases, ITGA5 ligands such as RGD motif (Arg-Gly-Asp) modified nano delivery system can actively deliver drugs to TNBC." (PMID 36463199, 2022). "Several factors have been shown to regulate ITGA5 expression in triple-negative breast cancer." (PMID 33420367, 2021). "ITGA5 could therefore contribute to the tropism of triple-negative breast cancer cells to bone." (PMID 33420367, 2021).
breast tumor (7 papers, 2015 to 2025). "Increased methylation of the ITGA5 gene has been associated with lower expression and increased invasiveness in breast tumors." (PMID 35216235, 2022). "In conclusion, this study shows the detection of cCAFs based on a novel biomarker, ITGA5, in blood in an orthotopic breast tumor xenograft model." (PMID 36831470, 2023). "We quantified ITGA5 expression levels in 427 radically resected primary breast tumors." (PMID 33420367, 2021). "Furthermore, multivariate analysis showed that ITGA5 expression in primary breast tumors is an independent prognostic factor for bone relapse." (PMID 33420367, 2021). "Having demonstrated that ITGA5 and pan-CK can be used for CAF and tumor cell detection, we employed the microsieve filtration system to capture cCAFs and CTCs in blood from orthotopic MDA-MB-231 breast-tumor-bearing mice." (PMID 36831470, 2023). "Increased CHRNA7 and ITGA5 expression correlates with poor prognosis in patients with various types of cancer including epidermoid carcinoma, while elevated CERK expression correlates with breast tumor recurrence." (PMID 37854069, 2023). "Mechanistically, NCOA1 has been shown to up-regulate Twist1, ITGA5, CSF-1, SDF1 and CXCR4 expression, which are partially responsible for promoting metastasis through potentiating breast tumor cell epithelial-mesenchymal transition (EMT), migration, invasion and macrophage recruitment." (PMID 26287601, 2015).
colon cancer (6 papers, 2021 to 2023). "ITGA5 is expressed in CAFs and is responsible for the tumor-promoting effect of CAFs in colon cancer." (PMID 35910200, 2022). "The expression of hsa-miR-330-5p in colon cancer tissue is significantly lower than that in adjacent tissues and negatively regulates the expression of integrin α5 (ITGA5), which affects the development of CC." (PMID 34337040, 2021). "It was found that DNASE1L3, ITGA5, BRAP, and NFE2L2 were related to the immune infiltration of colon cancer." (PMID 35252219, 2021).
leukemia (6 papers, 2012 to 2023). A malignant (clonal) hematologic disorder, involving hematopoietic stem cells and characterized by the presence of primitive or atypical myeloid or lymphoid cells in the bone marrow and the blood. "ITGB1, ITGB3, ITGA4, and ITGA5 were expressed in five of the six leukemia cell lines, and ITGB4 and ITGA6 were specifically expressed in the three EVI1high leukemia cell lines." (PMID 22295105, 2012). "To verify whether integrin α4 (ITGA4) is implicated in the adhesion of leukemia cells to MSCs, we knocked down ITGA4 and ITGA5 and examined cell adhesion." (PMID 37453060, 2023). "Subsequently, AMD3100 was added to the co-culture system, which weakened the expression of ITGA5 and ITGB1 in leukemia cells (P < 0.05)." (PMID 34733839, 2021).
liver cancer (6 papers, 2021 to 2025). An epithelial or non-epithelial malignant neoplasm that arises from the liver. "Our study also found that EMP2 downregulation led to a significant reduction in ITGA5 protein expression, weakening the invasion ability of liver cancer cells and resulting in fewer and smaller experimental lung metastases; conversely, overexpression had the opposite effect." (PMID 39866225, 2025). "Results revealed that high expression levels of ITGA5 were significantly correlated with worse OS and DFS in four types of gastrointestinal tumors, including colorectal, pancreatic, gastric and liver cancers." (PMID 33711961, 2021).
prostate carcinoma (6 papers, 2011 to 2024). A carcinoma that arises from epithelial cells of the prostate gland. "While no clear PIM-dependent changes in integrin activity or expression have previously been reported, we now found correlations between PIM1 or NFATC1 mRNA expression levels with ITGA5, both in PC-3 cells and in prostate cancer patient-derived samples." (PMID 31730483, 2019). "Most interestingly, the positive correlation between NFATC1 and ITGA5 increased along the Gleason score, with the strongest correlation in prostate cancer patients with Gleason ≥8." (PMID 31730483, 2019). "Silencing of an endogenous target gene was evaluated with antibody based immunofluorescence detection of integrin alpha-5 (ITGA5) in PC-3 prostate cancer cells transfected for 48 h on a CSMA with replicate spots of a validated ITGA5 siRNA." (PMID 21443765, 2011). "Additionally, the ITGA5-based antibody CTNO-95 promoted progression-free survival in patients with castration-resistant prostate cancer." (PMID 34375304, 2021). "In addition, radiation-induced upregulation of ITGB1 has been demonstrated in vitro and in vivo in prostate cancer cells, as well as upregulation of ITGA5 on colorectal tumor cells after X-ray irradiation." (PMID 34211843, 2021). "Maybe most interestingly in regard to our data on promotion of prostate cancer cell motility by PIM1 and NFATC1, there were several genes encoding regulators of the cytoskeletal actin network (INF2, FHOD1, ACTN3, CORO1B) and cell adhesion (COL6A2, PXN, ITGA5)." (PMID 31730483, 2019). "TAMs exert androgen deprivation resistance through activation of activin A, which ultimately leads to elevated fibronectin (FN1), FN1-integrin alpha 5 (ITGA5), and tyrosine kinase Src (SRC) network in prostate cancer cells." (PMID 38361941, 2024). "Our data prompted us to examine clinical prostate cancer samples for their expression levels of PIM1, NFATC1 and/or ITGA5 mRNAs." (PMID 31730483, 2019). "We compared the expression levels of eight integrin subunits (ITGA2, ITGA5, ITGAV, ITGB1, ITGB3, ITGB4, ITGB5, and ITGB6), HOXB13, HOXA11-AS, CCL2, CXCL12, and IBSP in prostate cancer tissues that had metastasized to bone, lymph nodes, lungs, liver, and other organs." (PMID 33514011, 2021).
atherosclerosis (5 papers, 2021 to 2025). A disease characterized by the build-up of fatty material and calcium deposition in the arterial wall resulting in partial or complete occlusion of the arterial lumen. "eNOS S1176A mice also exhibit significantly higher levels of integrin-α5 (ITGA5), a fibronectin receptor associated with increased inflammation and atherosclerosis." (PMID 38034389, 2023). "In rat atherosclerosis PCR array, Abca1, Bax, Bcl2, Bcl2a1, Cd44, Fabp3, Hbegf, Lypla1, Ptgs1, Selplg, Tgfb2, Tnc, and Vegfa had reverse trend between WT and MU groups, while the trends of Bcl2l1, Bid, Birc3, Cxcl1, Fas, Fn1, Itga2, Itga5, Lif, Nfkb1, Nr1h3, Ppard, and Sod1 were consistent." (PMID 34545275, 2021).
liver fibrosis (5 papers, 2015 to 2025). "After inhibiting ITGA5, it will reduce the expression of collagen in liver tissues, thereby alleviating the process of liver fibrosis." (PMID 34830238, 2021). "Studies have found that ITGA5 is also closely related to tissue fibrosis, when the expression of ITGA5 is inhibited, liver fibrosis will be alleviated." (PMID 34830238, 2021). "Classical fibrotic mediators and markers (including Tgfb1, Timp1, and Vcam1), collagen of the ECM (including Col4a1, Col4a2, Col16A1, and Col18a1) and cell surface adhesion and signaling integrin (Itga2, Itga5) were found to be differentially expressed in the enriched hepatic fibrosis pathways." (PMID 39747668, 2025). "In the liver, inhibiting the expression of ITGA5 can significantly alleviate liver fibrosis." (PMID 34830238, 2021). "Ten DEGs including PDGFra, PDGFrb, PDGFb, PDGFd, COL1A1, COL1A2, COL5A2, ITGA5, THBS1 and IL1R1, closely related to liver fibrosis, were chosen for the real-time qRT-PCR analysis." (PMID 26691002, 2015).
metastatic tumors (5 papers, 2017 to 2026). "As an example, the ITGA5 antagonist cilengitide has anti-cancer effects on metastatic tumors in animal models." (PMID 34375304, 2021). "The highest differentially expressed genes in metastatic (MET and PRI+) versus non-metastatic tumors (PRI-) and SES included PLAU, PLAUR, MMP1, MMP10, MMP13, ITGA5, VEGFA, and various inflammatory cytokine genes." (PMID 35480116, 2022).
non-small cell lung carcinoma (5 papers, 2018 to 2024). A group of at least three distinct histological types of lung cancer, including non-small cell squamous cell carcinoma, adenocarcinoma, and large cell carcinoma. "Some studies revealed the prognostic role of ITGA5 in non-small cell lung cancer through bioinformatics, which resulted as an independent prognostic predictor, and the five-year survival rate of patients with high ITGA5 expression was significantly reduced." (PMID 33335550, 2020). "In terms of mechanism, IGFBP2/ITGA5 enhances the expression of CXCL1 by activating STAT3, thereby promoting gefitinib resistance in non-small cell lung cancer." (PMID 38918360, 2024). "It was demonstrated that ITGA5 and ITGB1 are prognostic in non-small-cell lung cancer by integrin and gene network analysis." (PMID 33414898, 2020).